INS (insulin)
Diseases named in the same sentence as INS in open-access papers (continued):
Sharing a sentence is not in itself a finding about the gene and the disease.
Insulin resistance (continued). "At the follow-up time point insulin and insulin resistance were higher in CHR while comparing to CTR." (PMID 39085221, 2024). "The 24-h movement composition was associated with waist circumference, triglycerides, fasting serum insulin, and Homeostatic Model Assessment–insulin resistance (HOMA-IR) in both controls and women with PCOS." (PMID 39366675, 2024). "Fasting glucose, fasting insulin, adiponectin, and insulin resistance were insignificant predictors in the model." (PMID 38410303, 2024). "The effective prediction of preterm PROM can be achieved through the monitoring of serum HbA1c, insulin levels, and insulin resistance in patients with GDM." (PMID 39216124, 2024). "According to the dominant model, carriers of one or two risk alleles, rs1421085 (TC or CC), had significantly greater post-surgical weight, serum insulin, and insulin resistance than did carriers of the TT genotype." (PMID 38674326, 2024). "High iron is a risk factor for T2DM and affects most of its cardinal features, such as decreased insulin secretion, insulin resistance, and increased hepatic gluconeogenesis." (PMID 38612580, 2024). "Elevated 20-HETE contributes to HFD-induced obesity, insulin resistance, and impaired insulin signaling." (PMID 40452921, 2024). "Another risk factor for MAFLD development is the upregulation of miR-29 a/b/c which leads to insulin resistance through the block of Akt pathway and insulin signaling." (PMID 38662298, 2024). "T2DM is a prevalent multifactorial disorder that is characterized by low insulin secretion by pancreatic β-cells and impaired insulin action on peripheral tissues (insulin resistance), resulting in elevated blood glucose levels (hyperglycemia)." (PMID 39273144, 2024). "As the disease progresses, it generally transitions from an initial phase dominated by insulin resistance—albeit with some residual insulin production—to a later stage marked by significant insulin insufficiency, alongside persistent insulin resistance." (PMID 39770517, 2024). "Visceral adipose tissue stimulates insulin resistance, by increasing insulin and proinsulin excretion from the beta cell." (PMID 38541121, 2024). "Insulin resistance, a condition wherein cells in the body lose their sensitivity to insulin and blood glucose levels rise, is a feature shared by both disorders." (PMID 38255264, 2024). "At this stage, BCAA-deficient chow did not alter food intake, water intake, fasting blood glucose levels, and insulin resistance, as detected by glucose tolerance tests and insulin tolerance tests in both STZ/HFD and db/db mice." (PMID 39659577, 2024). "Defined as an impaired biological response of the body to insulin stimulation, peripheral insulin resistance has long been recognized to play a critical role in developing T2DM and in complications related to T2DM, including in the brain." (PMID 37611907, 2024). "Chronic exposure to high levels of FFAs can impair pancreatic β-cell function leading to reduced insulin secretion and insulin resistance." (PMID 39881810, 2024). "Excessive ROS production in mitochondria can activate inflammatory pathways, leading to impaired insulin signaling and insulin resistance." (PMID 39763653, 2024). "As the TyG-WC index was the only insulin surrogate index associated with plasma leptin and LAR after adjustment for BMI, this variable was used to identify an insulin resistance status, defined as a TyG-WC index above the 75th percentile." (PMID 38289144, 2024). "Homeostasis model assessment of insulin resistance (HOMA-IR) was calculated from fasting insulin and fasting glucose." (PMID 37935884, 2024). "As previously demonstrated, partial pancreatectomy resulted in severe insulin resistance and a parallel 50% decrease in insulin-stimulated glucose transport in adipocytes." (PMID 38426504, 2024).
Insulin resistance (continued). "The HOMA-IR test is a mathematical model that allows indirect assessment of insulin resistance and is calculated from the values of blood glucose and fasting insulin levels." (PMID 38673723, 2024). "This interaction between IL-6 and GSH insufficiency disrupts insulin signaling, promoting insulin resistance and impaired glucose metabolism." (PMID 39857603, 2024). "Insulin levels and homeostatic model assessment for insulin resistance (HOMA-IR) scoring were elevated, demonstrating developing insulin resistance (IR)." (PMID 38591148, 2024). "For example, butyrate, a short-chain fatty acid (SCFA) has been shown to positively influence insulin sensitivity and reduce inflammation, which are key factors in the pathogenesis of insulin resistance and T2DM." (PMID 39767626, 2024). "T2DM is a medical condition characterized by insufficient insulin production and release by the β-cells in the pancreatic islets, as well as decreased insulin sensitivity, commonly known as insulin resistance (IR)." (PMID 39335530, 2024). "Galectin-3 is involved in the development of insulin resistance through direct interactions with the insulin receptor, with altered insulin-regulated glucose metabolism in adipocytes, myocytes and hepatocytes." (PMID 38777863, 2024). "Insulin resistance typically triggers an excessive release of insulin by beta-cells, which further decreases the insulin sensitivity of tissues, leading to persisting hyperglycemia over time." (PMID 38675719, 2024). "Increased glycemia in diabetic patients is mainly attributed to two reasons: decreased insulin secretion or increased insulin resistance." (PMID 38212312, 2024). "Insulin resistance refers to a decrease in the sensitivity and/or reactivity of insulin signal transduction, resulting in increased glucose absorption after the ingestion or administration of glucose." (PMID 39056690, 2024). "Insulin resistance, a hallmark of T2DM, has been linked to lysosomal dysfunction, with the study suggesting that lysosomes play a pivotal role in insulin signaling and glucose metabolism." (PMID 39193017, 2024). "In a state of insulin resistance, the body’s tissues and cells respond insufficiently to insulin stimulation, leading to hyperglycemia." (PMID 38255878, 2024). "Inflammatory pathways like c-Jun N-terminal kinase (JNK) worsen insulin resistance, impacting insulin signaling." (PMID 38672148, 2024). "SCFAs help improve insulin secretion, reduce insulin resistance, suppress glucose production, and decrease food intake by regulating the secretion of hormones like GLP-1, leptin, and ghrelin, thereby playing a positive role in DM prevention and management." (PMID 39610877, 2024). "Insulin resistance triggers a compensatory elevation in circulating insulin levels, an augmentation in ovarian estrogen and adrenal androgen secretion, and a decrease in sex hormone-binding globulin concentration." (PMID 40302954, 2024). "In support of this latter scenario is the observation in mice that increased Akt-dependent insulin signaling was responsible for the development of insulin resistance after the start of a high-fat diet." (PMID 38791525, 2024). "We found that, insulin levels and insulin resistance increased during the follow-up period only in CHR, effect being largest in the CHRs converting to psychosis, independent of exposure to antipsychotics." (PMID 39085221, 2024). "Insulin signaling, as well as insulin resistance (IR), is a major contributor in the regulation of mood, behavior, and cognition." (PMID 39518747, 2024). "Elevated blood glucose levels not only exacerbate insulin resistance but also induce glucotoxicity, damaging insulin signaling pathways further." (PMID 39519193, 2024). "In the insulin resistance experiments, HFD/STZ model rats were found to be insensitive to insulin and to exhibit insulin resistance (p < 0.01)." (PMID 38952685, 2024).
Insulin resistance (continued). "The main conclusion of this study was that older Brazilian children with ASD have higher values for triglycerides, insulin levels, free fatty acids, and the HOMA index, indicating a higher risk for insulin resistance." (PMID 39595815, 2024). "For example, FFA are increased in the fasted state but can also increase due to insufficient peripheral insulin action to suppress adipocyte lipolysis as seen in insulin resistance." (PMID 38444015, 2024). "Biochemical changes characteristic of pregnancy were observed in all women, including increased insulin concentrations, heightened insulin resistance, and increased lipid concentrations toward the end of pregnancy." (PMID 39698038, 2024). "The characteristics of insulin secretion in the mice were observed through an intraperitoneal insulin resistance test." (PMID 38839927, 2024). "QWBZS was able to improve insulin resistance, regulate insulin secretion, increase hepatic glycogen synthesis, regulate lipid metabolism disorders, and reduce the levels of blood glucose, TC, and TG in T2DM mice." (PMID 39845797, 2024). "As T1D progresses, pro-inflammatory cytokines inhibit β-cell regeneration, stimulate peripheral insulin resistance, and maintain insulin inflammation." (PMID 39346923, 2024). "In PCO syndrome, there is a so-called “insulin resistance paradox”: insulin sensitivity is preserved in the ovaries, while insulin sensitivity is impaired in adipose, liver, and muscle tissues." (PMID 38337532, 2024). "In diabetic patients with insulin resistance, elevated blood insulin levels are typically observed due to the reduced responsiveness of cells to insulin." (PMID 39795285, 2024). "Pancreatic β-cell dysfunction leads to insulin insensitivity in target tissues and accelerates the development of insulin resistance." (PMID 39769097, 2024). "In children and adolescents with obesity the SPISE index can be proposed as an alternative to OGTT and other insulin-based methods for evaluating insulin resistance." (PMID 39649219, 2024). "HOMA-IR readings below 1 show the highest insulin sensitivity levels, with levels above 1.9 suggesting the onset of insulin resistance and above 2.9 indicating significant insulin resistance." (PMID 39590330, 2024). "Insulin resistance (IR), marked by reduced cellular responsiveness to insulin, and obesity, defined by the excessive accumulation of adipose tissue, are two intertwined conditions that significantly contribute to the global burden of cardiometabolic diseases." (PMID 39337290, 2024). "Excessive phosphorylation of AKT can result in its prolonged activation and insulin-resistance, as cells become less and less responsive to insulin." (PMID 38539237, 2024). "In the hypothalamic neuronal cell line N43/5, palmitic acid decreases autophagic influx and insulin sensitivity and induces insulin resistance via the excessive activation of GPR40." (PMID 39683565, 2024). "Glucose and insulin tolerance tests (GTTs and ITTs, respectively) unveiled that KO mice had severe glucose intolerance and insulin resistance." (PMID 38569495, 2024). "The evolution of the HOMA index within the studied groups provides insight into how different interventions or conditions can influence insulin sensitivity and insulin resistance in a given population." (PMID 38732523, 2024). "Our previous data suggest that the administration of α-LA attenuates insulin resistance, which is reflected in reduced levels of plasma glucose and insulin." (PMID 38794739, 2024). "Increased proinflammatory cytokines in the adipose tissue of obese individuals reduce insulin sensitivity, leading to insulin resistance." (PMID 39165513, 2024). "Significant improvements in Homeostatic Model Assessment for Insulin Resistance (HOMA2-IR) computed with fasting insulin were observed with retatrutide doses of 4 mg or greater, with changes up to −69.3% at 48 weeks (P < 0.001 versus placebo)." (PMID 38858523, 2024).
Insulin resistance (continued). "Insulin therapy is an essential component of periprocedural care post heart transplantation, as acute and chronic insulin resistance both lead to graft malfunction." (PMID 38365663, 2024). "Insulin and glucose levels assessed via fasting blood draw were used to calculate insulin resistance using the HOMA‐IR formula." (PMID 39579357, 2024). "Recent studies have also indicated that chronic inflammation and endoplasmic reticulum stress contribute to the dysregulation of insulin signaling pathways, exacerbating insulin resistance." (PMID 39125938, 2024). "Throughout this process, insulin resistance, characterized by systemic impairments in insulin signaling in tissues such as the hepatic, muscle, and adipose tissues, is the primary driver of disease progression." (PMID 39452917, 2024). "Enhancing insulin action is crucial for improving glucose intolerance, including the amelioration of insulin resistance." (PMID 39333851, 2024). "Neonatal and perinatal action of BPA at estrogen receptors in pancreatic β-cells results in increased insulin synthesis and release, and increased leptin levels, contributing to the eventual development of insulin resistance and impaired glucose tolerance." (PMID 38992091, 2024). "Following strong infection, the synergistic action of IFNγ and IL-1β on pancreatic β cells leads to an increase in insulin production that exceeds the levels required to compensate for skeletal insulin resistance." (PMID 39107476, 2024). "Hyperinsulinemia always coexists with insulin resistance until β cells are unable to produce the amount of insulin needed to balance the rising insulin resistance, at which point blood glucose levels rise and symptoms of glucose intolerance develop." (PMID 39049964, 2024). "It was determined that the body composition components, lipid profile indicators, insulin, glucose, insulin resistance, leptin, ghrelin, irisin, and MDA parameters examined in this study showed positive changes in the intervention groups." (PMID 39768899, 2024). "Several studies have demonstrated the potential of nanozymes in reducing insulin resistance and improving insulin sensitivity." (PMID 38711066, 2024). "Controversially, PEDF is demonstrated to induce insulin resistance in obesity in partial researches, and lipotropic ectopic deposition, impaired insulin signal transduction, mitochondrial dysfunction and inflammation are proposed to be potential mechanisms." (PMID 38375199, 2024). "Among children and adolescents with normal glucose tolerance, increased insulin resistance corresponds to heightened insulin secretion." (PMID 38550917, 2024). "Japanese women with GDM and a BMI over 25 kg/m2 can experience increases in insulin resistance requiring insulin treatment." (PMID 39803116, 2024). "In two groups of women, %ASM was associated negatively with homeostasis model assessment insulin resistance (HOMA-IR) and 2-h insulin (both p < 0.01 or less)." (PMID 39188637, 2024). "These chronic inflammatory states contribute to the induction of impaired insulin sensitivity (also called insulin resistance) and the development of type 2 diabetes." (PMID 38347961, 2024). "The percentage of effect that the first 70 days on the KD had on weight was 62% compared to 73% for serum insulin and 87% for HOMA-IR suggesting that a KD improves insulin resistance before weight loss becomes apparent." (PMID 39328462, 2024). "In the course of insulin resistance, there is a persistence of high levels of insulin in the blood, which leads to an abnormal mechanism." (PMID 39057041, 2024). "Using both fasting glucose and insulin values, we calculated the homeostatic model assessment for insulin resistance (HOMA-IR), an estimation of insulin resistance." (PMID 39439317, 2024). "The primary explanation for the link between insulin resistance and vascular endothelial dysfunction is impaired insulin action due to receptor resistance and its consequent hyperinsulinemia." (PMID 39610878, 2024).
Insulin resistance (continued). "As a result of insulin resistance induced by steroids, more insulin is required to achieve the same level of glucose control that would be maintained in the absence of steroids." (PMID 38510914, 2024). "Elevated FFAs can impair insulin signaling, leading to metabolic insulin resistance by inhibiting insulin-stimulated glucose uptake and suppressing nitric oxide production, which can affect vascular function." (PMID 39771045, 2024). "Impaired glucose uptake in some insulin-responsive tissues is considered a candidate mechanism for rapamycin-induced insulin resistance." (PMID 39637031, 2024). "Low levels of HOMA-IR designate higher insulin sensitivity, so high levels of HOMA-IR specify low insulin sensitivity, or indeed insulin resistance." (PMID 38233797, 2024). "The positive feedback loops consist of increased insulin resistance leading to higher insulin levels which in turn increases insulin resistance." (PMID 38572086, 2024). "In contrast, in obesity-induced insulin resistance, FATox at a fasting state is lower, and the ability to switch to CHOox in response to insulin stimulation is impaired." (PMID 38416072, 2024). "Elevated ceramide levels have been linked to insulin resistance and TNF-α-induced insulin desensitization." (PMID 39590846, 2024). "We performed an OGTT with a washout of the study drug after the intervention to eliminate the effects of the study drug on insulin secretion capacity, insulin resistance, and glucose tolerance." (PMID 39497800, 2024). "T2DM is the consequence of insufficient insulin secretion relative to insulin resistance with advanced age, excessive weight gain, and insufficient physical activity." (PMID 39295999, 2024). "Fasting insulin and glucose are used to calculate Homeostatic Model Assessment-Insulin Resistance (HOMA-IR)." (PMID 39516828, 2024). "Hepatic insulin resistance was observed with the elevated level of tumor necrosis factor-α (TNFα) via decreasing the insulin signaling and glucose transporter type 4 (GLUT4) expression." (PMID 38338579, 2024). "High androgen levels in patients with PCOS are highly affected by hyperinsulinemia and insulin resistance since insulin regulates ovarian function, and excessive insulin can negatively impact the ovaries." (PMID 39459443, 2024). "Note that individuals assigned male sex at birth who were treated with estrogens (and androgen depletion) as gender-affirming therapy developed insulin resistance, suggesting that in males, E2 improves insulin sensitivity in the presence of intact AR action." (PMID 39225098, 2024). "A high-fat/high-sucrose diet is commonly used as a model of diet-induced insulin resistance and impaired glucose homeostasis, shown by the increased fasting glucose concentrations and amplified glucose and insulin responses to IP-GTT." (PMID 38414818, 2024). "Although the underlying mechanisms remain unidentified, studies suggest that the inner ear is a direct target for insulin action and insulin resistance." (PMID 39064022, 2024). "Higher ATGL levels were observed in subcutaneous adipose tissues before EHC in patients with either insulin sensitivity or insulin resistance, suggesting that a similar ATGL regulation occurs in humans." (PMID 38561547, 2024). "It is well documented that in many non-communicable diseases such as PCOS, there is a strong relationship between ROS generation and glucose/insulin metabolism, which can be characterized by a dysregulated mitochondrial function and insulin resistance." (PMID 38540173, 2024). "The studies showed that the FMT had a positive impact on managing hyperglycemia and insulin resistance, which is evident in the decline of blood glucose and HBA1c levels and the rise of insulin and C-peptides." (PMID 39483608, 2024).